CD8A (CD8 subunit alpha)
Diseases named in the same sentence as CD8A in open-access papers (continued):
Sharing a sentence is not in itself a finding about the gene and the disease.
tumor (continued). "Based on pan-cancer analysis, we found that CD8A was positively correlated with most tumor-infiltrating cells, especially B cells, dendritic cells, CD8+ T cells, macrophages, regulatory T cells (Tregs), and follicular helper T cells." (PMID 37637055, 2023). "In eMSC-treated mice, primary tumor CD8α+ T-cell percentages significantly increased, but, similarly to total CD3ε+ T-cell percentages, CD4+ T-cell depletion did not affect this increase." (PMID 37928528, 2023). "Fn significantly reduced the αPD-L1-mediated increase in CD4+CD3+ and CD8a+CD3+ cells and the activity (GZMB+) of the infiltrated CD8a+ T-cell population in the tumor region." (PMID 37723150, 2023). "We observed that anti‐CD8α mAb treatment significantly eliminated the difference in tumor burden between the shNC and shPgam1 groups and dampened anti‐PD‐1 therapeutic efficacy." (PMID 37705495, 2023). "Researchers have proposed studying the mechanism of STING signal transduction in DC triggered by DNA derived from tumor cells by examining CD8α DC phagocytosis of apoptotic or necrotic tumor cells." (PMID 37781382, 2023). "The tumour sections were stained with anti-human CD45 antibody, anti-human CD4 antibody, anti-human CD8α antibody, anti-human Foxp 3 antibody and the distribution of T cells in tumours was immunohistochemically investigated." (PMID 36166071, 2023). "For example, SERPINA1 showed close connections to CD8A in CD8+ T cells, CD68 in tumor-associated macrophages, IRF6 in M1 macrophages, NRP1 in DCs, STAT3 and IL17A in Th17 in most digestive cancers." (PMID 37511325, 2023). "On the immune cell side, it has been demonstrated that FLASH-RT promotes better recruitment of CD3+ T cells to the tumor core compared to CONVi, as well as higher levels of cytotoxic CD8α+ T cells in the TME." (PMID 36798129, 2023). "Using a preclinical model of TNBC, we showed that our tumor-specific oncolytic VV was able to change the tumor microenvironment, attracting and maintaining mature cross-presenting CD8α+dendritic cells and effector T-cells." (PMID 37586771, 2023). "As another advantage, CAR-NKT cells allow DC cells to start a long-term anti-tumor function with T cells by inducing CD8+ T cell cross-priming with CD103+ CD8α licensing in murine models." (PMID 37158883, 2023). "In fact, some mice treated with vancomycin displayed an increase in CD8α+ dendritic cells (DCs) with supplemental decreases in tumor burden in an IL-12-dependent manner." (PMID 37009485, 2023). "The CD8α+ DC subset, which has been shown to play a critical role in the development of tumor-specific immune responses, specifically requires type I IFNs to prime protective tumor-specific immune responses in vivo." (PMID 36949244, 2023). "In marked contrast, CD8α depletion inhibited the significant eMSC-mediated increase in primary tumor CD4+ T-cell percentages." (PMID 37928528, 2023). "The distribution of CD8a+ T cells in the tumor periphery on day 7 was clear after both ICI and oBHV + ICI treatments, but a visibly larger number of CD8a+ T cells that infiltrated deep into the tumor tissue was observed with the triple combination." (PMID 36831636, 2023). "In the tumor microenvironment, Selplg-Sell and Lck-(Cd8a + Cd8b1) pairs were included in the significantly decreased pairs in Sephin1 group compared to normal." (PMID 36718369, 2023). "Further, we explored the correlation between pathological subtypes and the four types of tumor immune microenvironment classified based on CD8A and PD-L1 expression." (PMID 36845145, 2023). "HITT overexpression in 4T1 cells attenuated tumor growth under both conditions, but it suppressed tumor growth more evidently in the control mice (HITT/vector control: 25%–34%) than in anti-CD8α antibody–treated mice (HITT/vector control: 78%–80%)." (PMID 37014700, 2023).
tumor (continued). "This production of type I interferon by DCs in the tumor microenvironment is important for the cross-presentation of CD8α DCs and the generation of tumor antigen-specific CD8+ T cell responses in vivo." (PMID 37781382, 2023). "Among 232 ARGs, IFNG was generally significantly correlated with tumor immunotherapy biomarkers (PD-L1, CD8A and cytotoxic T lymphocytes (CTL))." (PMID 36756126, 2023). "Total number and frequencies of tumor-infiltrating cytotoxic CD8a+ T cells were comparably augmented by any of our treatments." (PMID 37529399, 2023). "Cd8a was not significantly upregulated; however, Cd1d1 was, suggesting the involvement of invariant NKT cells at the secondary tumor site instead of more conventional CD8+ CTLs." (PMID 37345658, 2023). "In contrast, CD8α+ cell accumulation within tumor and adjacent normal breast was marginally different in ETBF-infected mice." (PMID 37503343, 2023). "The IRE1α-XBP1 axis was also shown to be crucial in the tumor antigen cross-presentation of CD8α+ conventional DCs, and deficiency of XBP1 in CD8α+ DCs resulted in a defective phenotype and antigen-presenting capacity." (PMID 35884393, 2022). "The second model is composed of large epithelial tumor compartments and a stromal compartment with a CD8a+ region." (PMID 35121992, 2022). "Based on the obtained expression profiles, the primary tumor tissues were categorized into immunological cold or hot tissues (presence of CD8α, CD11c, CD16 and CD68); the impact of immune cell infiltration on event-free survival was established." (PMID 36139700, 2022). "The CD8α hinge and transmembrane domain play an important role in anti-tumor function and safety of CAR-T cells." (PMID 35392217, 2022). "Analyses of removed tumors using immunofluorescence (immunohistochemistry) revealed that STX6 knockdown significantly increases the infiltration level of CD8α in the tumor microenvironment." (PMID 36612024, 2022). "TLR3 in TME is mainly expressed in Batf3-positive dendritic cells (DCs) (CD141+ DCs in human, CD8a+ and CD103+ DCs in mouse) and tumor associated macrophages (TAMs)." (PMID 35413927, 2022). "We observed that CD8α mAb treatment significantly enhanced tumor burden by depletion of CD8+ T cells in tumor." (PMID 35347072, 2022). "Next, we found a higher percentage of CD8A-positive cells in the tumor tissues of mice given anti-GD2 mAb plus MβCD than that in the other three groups." (PMID 36284313, 2022). "CD103+CD11c+ DCs also outnumbered CD8α+CD11c+ DCs in tumor tissues of DEXP&A2&N-treated orthotopic HCC mice, indicating the stronger capacity of CD103+CD11c+ DCs to internalize and cross-present cellular neoantigens." (PMID 35488312, 2022). "Depletion of CD8+ T cells was carried out by administration of anti-CD8α to mice bearing an orthotopic NASH-HCC tumour and alongside AZD5069/anti-PD1 treatment." (PMID 35477863, 2022). "Pan-cancer analysis showed that CD8A was highly associated with TMB, stemness and MSI among several tumor types including BCa." (PMID 36230788, 2022). "Among the 623 patients with paired tumor–normal samples, we observed a positive correlation between tumor and adjacent normal tissue for GSAct (Pearson’s r = 0.31, p < 0.001) and CD8A single gene (Pearson’s r = 0.46, p < 0.0001)." (PMID 36376974, 2022). "Some, like CD69 were upregulated at d2 in the tumor, and a number of genes including CD8a and CD8b1 are downregulated in the tumor at d2; however, these changes were not significant when corrected for multiple comparisons." (PMID 36056093, 2022). "RT-qPCR analysis of mRNA levels in 10 OSCC tumor tissues revealed that the mRNA levels of IGF2BP2 was also negatively correlated with that of CD8A." (PMID 35299748, 2022). "Given the crucial role of CD8α+ cDC1s in suppressing GvHD while promoting GvL responses, the role of pre-cDC1s in induction of alloreactive T-cell responses and anti-tumor responses is of great clinical significance for HCT." (PMID 35980974, 2022).
tumor (continued). "On immunohistochemistry of tumor sections, infiltrating CD8α+ T lymphocytes constituted a small fraction of tumor cells." (PMID 35250391, 2022). "Recent studies have demonstrated that administering a TLR3 agonist enhanced the maturation of CD8α+ DCs, which in turn promoted cross-presentation in the tumor microenvironment and tumor regression 54,55." (PMID 34975324, 2022). "Here, we demonstrate that DEXP&A2&N resulted in recruitment, specific accumulation and activation of cross-presenting CD103+CD11c+ and CD8α+CD11c+ DCs in tumor of orthotopic HCC mice after intravenous administration." (PMID 35488312, 2022). "To further explore the effect of anti-GD2 mAb plus MβCD on tumor immunity, we detected the protein expression of CD8A, caveolin-1, CXCL9, and CXCL10 by IHC staining." (PMID 36284313, 2022). "Further studies indicated that live EG7 cells cross‐dressed CD8α+ DCs with functional p‐MHCI antigens in tumor‐draining lymph nodes." (PMID 35959554, 2022). "The requirement for CD8+ T cells for the anti-tumour effect of combination therapy was additionally confirmed by performing anti-CD8α-mediated depletion in tumour-bearing DEN/ALIOS mice treated with combination AZD5069/anti-PD1." (PMID 35477863, 2022). "Depletion of CD8 T cells augmented metM-WnTlung cell growth, resulting in greater ex vivo tumor mass among CD8α-treated mice at all measured timepoints (13, 17, 21 and 25 days following tumor injection) compared to isotope-treated controls." (PMID 36686775, 2022). "On microsection slides, CD8α+ effector T-cells were seen infiltrating the tumor, but this constituted only a very small fraction compared to malignant tumor cells." (PMID 35250391, 2022). "One proposed mechanism is that CD8α+ DCs engulf apoptotic or necrotic tumour cells, and tumour cell-derived DNA triggers STING signalling in DCs." (PMID 36106115, 2022). "We found that CD8α mAb cotreatment aggravated tumor burden by eliminating CD8+ T cells in both Hepa1-6 and H22 subcutaneous and orthotopic tumor models." (PMID 36509766, 2022). "Overall, in the NHS cohort we found that GSAct and CD8A each differed significantly between tumor and normal samples (p < 0.0001 and 0.002, respectively)." (PMID 36376974, 2022). "An overview of the main tumor-infiltrating immune cells identified by flow cytometry showed a higher proportion of conventional dendritic cells (cDCs) and CD8α DCs in the T. usneoides group compared with the control group." (PMID 36358804, 2022). "Aside from anti-viral CD8+ T-cell responses, CD8α+ cDC1s also play a seminal role in promoting anti-tumor CD8+ T-cell responses via cross-presentation and cross-priming." (PMID 35980974, 2022). "As expected, CD11c+ DCs including CD103+, CD8α+ and CD11b+ DCs were significantly expanded in blood of tumor-bearing mice after repeated subcutaneous injections of Flt3L, confirming the effectiveness of Flt3L." (PMID 35488312, 2022). "Tumor antigens are carried in small vesicles inside DCs that can also be transferred among DC subsets enabling also resident CD8α+ DCs to prime CD8+ T cells." (PMID 35626062, 2022). "The cross-presentation of tumor-derived antigens is then stimulated by this IFN-β acting on the CD8α+ DC subset, resulting in the cross-priming of CD8+ T cells specific for the tumor antigen." (PMID 36499305, 2022). "We evaluated tumor immune cell infiltration by monitoring changes in the expression of Cd8a, Cd68, and Nkp46, immune cell markers for cytotoxic T cells, macrophages, and natural killer cells, respectively." (PMID 36187936, 2022). "Owing to their responsibility for the initiation of the “cancer-immunity cycle”, cDC1 (CD8α+CD103+BATF3+ CLEC9A+XCR1+) is identified as a critical APC subset for tumor antigen drainage and robust T cell activation." (PMID 36244976, 2022).
tumor (continued). "Immunohistochemistry of EL4 tumor tissue in our study confirmed the presence of CD8α+ effector T-cells infiltrating the tumor, but this constituted only a small fraction compared to malignant tumor cells." (PMID 35250391, 2022). "A similar configuration with the CD8α transmembrane domain had anti-tumor activity that was comparable to 4-1BB/ICOS CAR-T cells with the 4-1BB domain in the proximal position and a CD8α transmembrane domain." (PMID 35053463, 2022). "The involvement of CD8A gene in the proposed signature seems to confirm the well-known positive prognostic role of CD8+ tumor-infiltrating lymphocytes (TILs) in several cancers, including HNSCC." (PMID 36231138, 2022). "Thus, we delineated the correlation analysis between CD8A and immunosuppressive cells, containing myeloid-derived suppressor cells (MDSCs), regulatory T cells (Tregs), cancer-associated fibroblasts (CAFs), and M2 subtypes of tumor-associated macrophages (M2-TAMs)." (PMID 36035168, 2022). "Tumor-killing assays revealed that T-cells primed with CD8α-depleted DCs ex vivo induce greater killing of A20 B-cell leukemia cells, particularly when antigen (Ag) is limited." (PMID 35980974, 2022). "Th17 cells also induce a CTL response by expanding CD8a+ DCs, a cell type critical for cross-presenting tumor antigens to CD8+ T cells." (PMID 36248881, 2022). "Irradiated tumor growth was still reduced in the combination of high dose irradiation with C4 even under CD8α administration." (PMID 35565217, 2022). "As expected, a significant decline in the number of CD11c+ DCs, particularly CD103+CD11c+ and CD8α+CD11c+ DCs, was observed in tumor-infiltrating lymphocytes of DEXP&A2&N-treated Batf3−/− compared to wild-type mice." (PMID 35488312, 2022). "We next inspected tumor-infiltrating T cells, a heterogeneous population that includes effector T cells such as CD8a+ cytotoxic T cells (CTL) and natural killer T cells (NKT), as well as CD4+ helper T cells and Tregs." (PMID 36105861, 2022). "This study also provides a rational basis for elucidating the effect of phthalate exposure on tumor immunity and vaccine response, in which CD8α+ DCs play important roles." (PMID 35663974, 2022). "After PPI network loaded into the cell landscape, CD8A was located in the top 10 nodes, and the PPI network of CD8A composed of genes/proteins involved in immunomodulation, which indicates that CD8A plays an important role in tumor immune regulation." (PMID 35572597, 2022). "Although expression analysis showed only small changes in CD8+ T cell markers, immunohistochemical staining of the tumours for CD8a showed increased numbers of infiltrating CD8+ cells with drug treatment." (PMID 34359633, 2021). "CD8α:MyD88-expressing T cells improved antitumor responses in mice and was associated with TME alterations including generation of a unique tumor cytokine/chemokine signature, improved T-cell infiltration with reduced markers of T-cell exhaustion." (PMID 34344725, 2021). "We analyzed the relationship between CD3D and currently known gene sets in the tumor microenvironment and verified the expression association between CD3D and CD8A in two other cohorts, GSE29721 and GSE121248." (PMID 34124275, 2021). "The combination treatment showed a 4-fold increase in systemic TNFa production and a 2.6-fold increase in Cd8a expression in tumor tissues, suggesting strong cell-mediated immune responses against the tumor." (PMID 34959344, 2021). "CD8A is considered a marker of T cells, and the expression of CD8A is well correlated with the diversity of the TCR repertoire across tumor types." (PMID 34344966, 2021). "Tumor gene expression analysis was also performed, demonstrating an elevation in CD8-α and IFN-ɤ mRNA after T-VEC administration." (PMID 33803762, 2021). "Detecting co-expression of CD3 and CD8a molecules can be used to identify the presence of tumour-infiltrating CD8+ T lymphocytes." (PMID 33809369, 2021).
tumor (continued). "We reveal that PTEN mRNA expression is significantly positively correlated with CD4/CD8A gene expression and T cells infiltration especially T helpers cells, central memory T cell and effector memory T cells in multiples tumor types." (PMID 33874915, 2021). "Two independent studies have demonstrated that endogenous IFN-I signaling is critical for the innate immune recognition of a growing tumor through signaling on CD8α+ DCs12,13." (PMID 34620867, 2021). "Adoptive transfer of TEG011_CD8α cells in humanized HLA-A*24:02 transgenic NSG (NSG-A24:02) mice injected with tumor HLA-A*24:02+ cells showed superior tumor control in comparison to TEG011, and to mock control groups." (PMID 34759930, 2021). "Tumor cDC1 clusters express the dermal DC marker Cd103 (Itgae), whereas the LN population expresses CD8a marker specific to LN resident dendritic populations." (PMID 33763348, 2021). "In our study, LTA was positively correlated with CD8+ T-cell infiltration and its markers’ expression after adjusting by tumor purity, such as CD8A, CD8B, and IL2RA." (PMID 35155447, 2021). "Conventional CD8α+ DCs appear to be critical APCs for cross-presentation of neoantigens for tumor rejection by T cells." (PMID 34595122, 2021). "In conclusion, although the number of analyzed bone marrows was limited, our data imply that TEG011_CD8α effectively cleared tumor cells in bone marrow, emphasizing the role of CD8α co-stimulation for better in vivo tumor control of TEG011 cells." (PMID 34759930, 2021). "To dissect their individual contributions to tumor regression, we depleted CTLs alone, NK cells alone, or both effector cell types using antibodies specific to CD8α (CTL depletion) or NKp46 (NK cell depletion)." (PMID 34081628, 2021). "Distinct tumor microenvironment immune types have been described, mainly based on the level of CD8A and PD-1 expression, with the intention to standardize a more comprehensive score to be used as a prognostic marker." (PMID 33562338, 2021). "Overall, our data indicate that introduction of transgenic CD8α on TEG011 cells effectively improves in vivo tumor control and better T cell infiltration into bone marrow." (PMID 34759930, 2021). "Despite the significant in vivo tumor control, we observed only a trend towards an improved overall survival for TEG011_CD8α-treated mice." (PMID 34759930, 2021). "For this reason, all tumor slices stained for CD8α were co-stained for FOXP3 expression and the ratio between the two was assessed within individual mice." (PMID 34253827, 2021). "Treatment with OVA + CD8α ALN-1 caused a significant delay in tumor growth over the treatment period, however, tumor control was transient and volumes rapidly caught up with lesion sizes observed in controls on treatment discontinuation." (PMID 34772757, 2021). "PD-L1 signal was diffusely distributed among neoplastic cells, whereas PD-1 and CD8A were localized in tumor infiltrating lymphocytes." (PMID 34209830, 2021). "We provide evidence that TEG011_CD8α effectively cleared tumor cells in bone marrow and elicited better tumor control against human HLA-A*24:02-expressing tumor cells." (PMID 34759930, 2021). "The systemic cGAMP mimetic SR-717 activated the STING signaling pathway, promoted CD8+ T-cell, NK cell, and CD8α+ DC activation, and significantly inhibited tumor growth." (PMID 33859752, 2021). "Vancomycin treatment induced an increase of systemic CD8α+ DCs, tumor-associated antigen cross-priming with antitumor CD8+ T cell elicitation, and tumor growth inhibition in mice, via decreasing SCFAs." (PMID 34589427, 2021). "Systemic delivery of CD8α ALN-1 can thus safely delay tumor growth over the treatment period by targeting CD8α+ cells." (PMID 34772757, 2021). "Upregulation of NPTX2 in cold tumor negatively correlated with the expression of CD8A, GZMB, and IFNG, and knockdown of NPTX2 increased the production of CCL4." (PMID 34258887, 2021).